ERCC5 (ERCC excision repair 5, endonuclease)
Diseases named in the same sentence as ERCC5 in open-access papers (continued):
Sharing a sentence is not in itself a finding about the gene and the disease.
tumor (26 papers, 2011 to 2025). "The expression levels of the three genes of interest involved in the NER pathway (i.e., ERCC1, ERCC2, and ERCC5) were obtained from diagnostic FFPE tumor samples." (PMID 39735668, 2025). "We showed loss of the wild-type allele in tumours from carriers of ERCC5 c.2556A>G, NEIL1 c.248G>T; p.Gly83Asp or NTHL1 c.244C>T; p.Gln82Ter." (PMID 36969007, 2023). "For levels of gene expression, Kaplan–Meier (KM) estimator and hazard ratios (HR) indicated that in 3 out of 33 TCGA tumor types, low (below mean) ERCC5 expression was a risk factor correlating with poor patient survival." (PMID 34966786, 2021). "Whereas higher expression of SOX10, OCLN, ACSL4, XIAP, and ERCC5 was associated with a lower risk of death from the tumor (HR < 1)." (PMID 33153038, 2020). "Tumour DNA from ERCC5, NEIL1 and NTHL1 variant carriers exhibited loss of the wild-type allele." (PMID 36969007, 2023). "The higher gene expression of ERCC1, ERCC2, and ERCC5 in tumor samples compared to healthy control is consistent with previous studies that reported high tumor tissue levels of NER pathways genes, mainly ERCC1, in SCLC and in other solid tumors." (PMID 39735668, 2025). "mRNA expression analysis and single nucleotide polymorphism (SNP) characterization of three NER pathway genes—namely ERCC1, ERCC2, and ERCC5—were performed on patient tumor samples." (PMID 39735668, 2025). "We identified three tumor types, which were also those with higher ERCC5 expression than in controls." (PMID 34966786, 2021). "We then investigated if a distinct genotype combination of ERCC1, ERCC2 and ERCC5 genes could influence the expression levels of these genes in the tumor tissue." (PMID 35955506, 2022). "However, we observed no LOH in tumour DNA from one carrier each of ERCC5 or NEIL1 variants and two carriers of NTHL1 variant." (PMID 36969007, 2023). "NER defects make tumor cells less sensitive to trabectedin damage and high expression levels of ERCC1 and XPG/ERCC5 (“signs” of a proficient NER machinery) have been described as predictive of better response to trabectedin treatment." (PMID 36110934, 2022). "Gene expression analysis of 4 genes (BRCA1, CUL4A, ERCC1, and ERCC5), involved in the DNA damage repair (DDR) machinery, was performed in 66 surgical tumor samples." (PMID 32365979, 2020). "Indeed, in 11/15 tumor–normal pairs, ERCC5 expression was not elevated relative to matched controls." (PMID 34966786, 2021).
infection (1 paper, 2012). The state of being infected such as from the introduction of a foreign agent such as serum, vaccine, antigenic substance or organism. "ERCC5 was related with more infection (OR = 1.721, P = 0.017)." (PMID 23118991, 2012).
ERCC5 also shares sentences with these, for which no sentence is quoted: neurological disorders (4 papers); Fanconi anemia (3); neuroblastoma (3); neurodevelopmental disorder (3); stomach cancer (3); esophageal squamous cell carcinoma (2); genetic diseases (2); head and neck cancer (2); prostate carcinoma (2); trichothiodystrophy (2); anemia (1); arthrogryposis (1); atrophic gastritis (1); autosomal recessive disease (1); breast invasive carcinoma (1); breast tumors (1); chordoma (1); Cognitive impairment (1); coronary artery disease (1); Erythema (1); fibrosarcoma (1); gastric diseases (1); genodermatosis (1); glaucoma (1); glioma (1); hearing loss (1); heart failure (1); Hyperglycemia (1); Hypertension (1); hypopharyngeal cancer (1).
A further 31 diseases each share a sentence with ERCC5 in 1 paper.